RAC3 (Rac family small GTPase 3)
Diseases named in the same sentence as RAC3 in open-access papers (continued):
Sharing a sentence is not in itself a finding about the gene and the disease.
bladder cancer (22 papers, 2020 to 2025). "RAC3 expression within bladder cancer tissues has been found to be linked to both the density of immune cells within the tumor microenvironment and the expression patterns of genes that are pivotal in the modulation of immune checkpoints." (PMID 39351351, 2024). "The bioinformatics analyses found RAC3 levels were elevated in bladder cancer tissues and were associated with a poor prognosis in bladder cancer." (PMID 38847477, 2024). "RAC3 is highly expressed in bladder cancer, and is associated with pathological grades and stages; in addition, RAC3 upregulation correlates with poor prognosis." (PMID 37056933, 2023). "RAC3 knockdown, another member of the Rho GTPase subfamily, led to increased autophagy via the same pathway in bladder cancer cells." (PMID 40072059, 2025). "RAC3 enhances proliferation and metastasis in bladder cancer cells by activating the JAK/STAT signaling pathway mediated by PYCR1." (PMID 40123831, 2025). "The underlying mechanism involves RAC3's regulation of the PI3K/AKT/mTOR pathway to modulate autophagy, influencing the biological activity of bladder cancer cells." (PMID 38217031, 2024). "Further in-depth investigations are warranted to dissect the complex interplay of RAC3 in tumor biology and to harness its full potential in bladder cancer management." (PMID 39351351, 2024). "Our research revealed a correlation between elevated RAC3 levels and diminished sensitivity to specific therapeutic agents, such as mitoxantrone, a chemotherapeutic agent for bladder cancer, as well as SB505124 and VE-822." (PMID 39351351, 2024). "This study indicates that the level of RAC3 expression in bladder cancer tissues is notably elevated compared with that in normal tissues." (PMID 39351351, 2024). "Building on these findings, we validated the regulatory role of RAC3 in the clinical and pathological characteristics, immune microenvironment, and chemoresistance of bladder cancer at the bioinformatics level." (PMID 39351351, 2024). "By employing RNA interference to knock down RAC3 expression, we observed notable suppression of the proliferative, migratory, and invasive capabilities of bladder cancer cells." (PMID 39351351, 2024). "Plasmid transfection was used to overexpress or silence the expression of RAC3 in bladder cancer cells resistant to cisplatin (BIU-87-DDP)." (PMID 38847477, 2024). "The findings underscore the strong correlation between RAC3 expression and the prognosis, including survival rates at the specified time points, for patients with bladder cancer." (PMID 39351351, 2024). "Our research revealed that RAC3 is markedly overexpressed in bladder cancer tissues and cells compared with their normal counterparts and that this overexpression is linked to the severity of malignant characteristics and an unfavorable prognosis for patients." (PMID 39351351, 2024). "The role of RAC3 in bladder cancer (BLCA) was explored through a series of analyses focusing on its expression levels in BLCA tissues and cell lines." (PMID 39351351, 2024). "This refined investigation provides reference value for further exploration into the role of RAC3 as a potential biomarker for chemoresistance and its implications for personalized therapeutic strategies in bladder cancer management." (PMID 39351351, 2024). "According to the results of this study, RAC3 has greater potential for early diagnosis of bladder cancer and improving patient prognosis." (PMID 37728806, 2024). "Influences of RAC3 in the grade, stage, distant metastasis, and survival rate of bladder cancer were also examined." (PMID 38847477, 2024). "Taken together, these observations highlight the putative role of RAC3 as a central modulator of the proliferative, invasive, and metastatic activities of bladder cancer, suggesting its potential as a novel therapeutic target for BLCA." (PMID 39351351, 2024).
bladder cancer (continued). "Testing the expression of RAC3 in serum and urine of high-risk individuals with bladder disease symptoms or with a family history of the disease, and performing more detailed examinations if abnormal results are found, could help in the early detection of bladder cancer patients." (PMID 37728806, 2024). "Both assays consistently indicated that the attenuation of RAC3 expression substantially compromised the invasive and migratory capabilities of bladder cancer cells." (PMID 39351351, 2024). "Bioinformatics techniques were used to investigate the expression of RAC3 in bladder cancer tissues." (PMID 38847477, 2024). "Our research revealed that RAC3 expression modulates the signaling pathways of B- and T-cell receptors, which are integral to the immune response, in bladder cancer." (PMID 39351351, 2024). "In an effort to decipher the potential interplay between RAC3 expression levels and the aggressive behavior of bladder cancer cells, we strategically utilized siRNAs to silence RAC3 in BLCA 5637 cells and T24 cells." (PMID 39351351, 2024). "We stratified patients into high- and low-expression cohorts using the median RAC3 expression level as the cut-off to elucidate the correlation between RAC3 expression and chemoresistance in bladder cancer." (PMID 39351351, 2024). "In terms of prognosis, RAC3 can be considered as a new therapeutic target, leading to the research of novel targeted drugs, which is of great significance for bladder cancer patients with upregulated RAC3 expression." (PMID 37728806, 2024). "I In this comprehensive study, we explored the intricate role of Ras-related C3 (RAC3), a pivotal member of the Rho subfamily of Ras proteins, in the modulation of bladder cancer (BLCA) progression." (PMID 39351351, 2024). "RAC3 is highly expressed in bladder cancer cells, and stimulates proliferation and migration of bladder cancer cells via PYCR1-mediated JAK/STAT pathway activation." (PMID 37056933, 2023). "Relationship between different expression groups of RAC3 and clinical characteristics in bladder cancer in TCGA." (PMID 35847878, 2022). "Second, additional studies are needed to confirm when does RAC3 begin to promote and to what extent it promotes bladder cancer occurrence (or progression)." (PMID 35847878, 2022). "Combined, we suggest that the RAC3 inhibition induces autophagy to impair the migration of bladder cancer cells via the PI3K/AKT/mTOR pathway." (PMID 35847878, 2022). "RAC3 is highly expressed in bladder cancer tissues and can promote the proliferation, migration, and invasion of bladder cancer cells." (PMID 33888644, 2021). "Existing research indicates that RAC3 can influence autophagy in bladder cancer cells, but whether RAC2 exhibits a similar mechanism in other malignancies requires further investigation." (PMID 40072059, 2025). "This suggests that RAC3 may impact the progression of bladder cancer by modulating autophagy through the PI3K/AKT pathway." (PMID 38217031, 2024). "The development of drugs aimed at modulating RAC3 activity could offer a novel approach to combat bladder cancer, particularly for patients facing resistance to existing treatments." (PMID 39351351, 2024). "We could indicate that inhibiting the expression of RAC3 may enhance the sensitivity of bladder cancer cells to gemcitabine." (PMID 38570787, 2024). "Furthermore, at the cellular level, we confirmed the impacts of RAC3 on the proliferation, migration, invasion, and chemokine expression of bladder cancer cells." (PMID 39351351, 2024). "Data from 432 bladder cancer patients within TCGA database, which included 413 tumor tissues and 19 normal tissue samples, were divided into two groups based on the median expression of the RAC3 mRNA." (PMID 39351351, 2024). "The correlation between RAC3 and poor prognosis in bladder cancer has been established." (PMID 38217031, 2024).
bladder cancer (continued). "Our research indicates that RAC3 potentially modulates the expression of chemokines, reshaping the immune microenvironment and mediating the development of chemotherapy resistance in bladder cancer." (PMID 39351351, 2024). "RAC3 in BIU-87-DDP cells expressed a higher level than normal bladder cancer cells." (PMID 38847477, 2024). "This insight into the multifaceted role of RAC3 in the immune landscape of bladder cancer may provide novel avenues for therapeutic intervention and a better understanding of the complex dynamics at play in cancer immunology." (PMID 39351351, 2024). "Our study demonstrates that RAC3 is highly expressed in bladder cancer and is correlated with the clinical and pathological features of patients, suggesting that RAC3 may facilitate the progression of bladder cancer." (PMID 39351351, 2024). "In addition, the focus of this study was to investigate this clinical phenomenon and did not address the specific mechanism of this relationship between RAC3 and bladder cancer." (PMID 37728806, 2024). "Interestingly, when RAC3 was knocked down, the growth and migration of bladder cancer cells were inhibited through the PI3K/AKT/mTOR pathway-mediated autophagy induction." (PMID 37056933, 2023). "Moreover, upregulation of RAC3 in bladder cancer predicted an adverse clinical outcome and increased tumor immune response." (PMID 34329197, 2021). "However, how RAC family small GTPase 3 (RAC3) affects the proliferation, migration and invasion of cisplatin-resistant bladder cancer cells remains unclear." (PMID 38847477, 2024). "However, the correlations between Rac3 expression and the clinicopathological characteristics and prognoses of patients with bladder cancer (BC) remain unclear." (PMID 34257551, 2021). "Our study aimed to clarify the interaction between the RAC3 protein and the TME in bladder cancer (BLCA) by quantifying immune cell infiltration with the ESTIMATE algorithm." (PMID 39351351, 2024). "In normal bladder cancer cells (T24, 5637, and BIU-87) and cisplatin-resistant bladder cancer cells (BIU-87-DDP), the expression of RAC3 was detected separately with Western blotting." (PMID 38847477, 2024). "In conclusion, the collective observations from our study underscore the potential of RAC3 as a valuable therapeutic target in bladder cancer, particularly for those who may not benefit from existing immunotherapies." (PMID 39351351, 2024). "Furthermore, Professor Wang's team discovered that knocking down RAC3 can inhibit the proliferation and invasion of bladder cancer cells without inducing apoptosis." (PMID 38217031, 2024).
colon carcinoma (9 papers, 2017 to 2025). "We found that RAC3 overexpression was mainly associated to CD133+ side-population of colon cancer cells and also to early and advanced stages of colon cancer, involving increased expression of mesenchymal and stem markers." (PMID 29464039, 2018). "A previous study has reported that RAC3 affected the sensitivity to apoptosis and autophagy of colon tumour cells induced by chemotherapeutic drugs." (PMID 37386813, 2023). "CNVs specific for MSS colon cancer IntOMICS identified edges from CNV to associated GE in five out of six genes of interest: KRAS, MYC, BIRC5, RAC3, and SMAD4." (PMID 35996085, 2022). "Moreover, it has also been reported that RAC3 inhibits apoptosis in colon cancer to influence chemotherapy sensitivity." (PMID 40123831, 2025). "Studies investigating the nuclear receptor coactivator, RAC3, indicate that it functions in many biological processes and tumorigenesis, it has a clear role in the development of resistance to chemotherapy in colon cancer cells through autophagy and apoptosis inhibition." (PMID 38200409, 2024). "For instance, RAC3 is regulated by ABL1, and this enhanced regulation has been shown to contribute to chemoresistance in colon cancer cells and support the maintenance of cancer cell stemness." (PMID 40585960, 2025). "The sensitivity to 5-fluorouracil and oxaliplatin in colon cancer cells HT-29, HCT 116 and Lovo cell lines, expressing high or low natural levels of RAC3, was investigated using viability assays." (PMID 29209153, 2017).
glioblastoma (7 papers, 2011 to 2023). The most malignant astrocytic tumor (WHO grade IV). "Silencing of either Rac1, Rac2 or Rac3 also inhibits glioblastoma cell migration and invasion in vitro." (PMID 31514269, 2019). "Rac1, Rac2 and Rac3 promote cell proliferation of glioblastoma cells that form tumor spheres, while these colonies are reduced in number and size by silencing either Rac GTPase." (PMID 31514269, 2019). "In our zebrafish transplantation model, we also observed a role of not only Rac1, but also Rac2 and Rac3 in angiogenesis induced by glioblastoma tumorspheres." (PMID 28160553, 2017). "The relative levels of Rac1 and Rac3 in PCa are similar to what has been shown in glioblastoma cells." (PMID 21776386, 2011). "Rac1, Rac2 and Rac3 are required for the growth, migration and invasion of glioblastoma cells." (PMID 31514269, 2019). "To investigate whether Rac proteins can serve as therapeutic targets for glioblastoma, especially for GSCs or stemloids, we examined the potential roles of Rac1, Rac2 and Rac3 on the properties of tumorspheres derived from glioblastoma cell lines." (PMID 28160553, 2017). "To examine if Rac2 and Rac3, besides Rac1, also promote the migration and invasion of glioblastoma stem-like cells as they do in normal cells, we used the tumorspheroid cells derived from U251-MG that stably express shRNA or scramble shRNA to perform the cell migration assay using Transwell." (PMID 28160553, 2017). "For example, in addition to Rac1, Rac2 and Rac3 knockdown in glioblastoma stem cells showed a dramatic decrease in their invasive and migrative capabilities, confirming that Rac proteins in general do play a crucial and necessary role in the invasion of GBM cells." (PMID 32089990, 2020). "Rac1 and Rac3 have previously been reported to have opposite effects on neuronal cell adhesion, and only Rac1 and not Rac3 depletion reduced lamellipodia in glioblastoma cells." (PMID 29510700, 2018). "From these results, we conclude that the influence of Rac2 and Rac3 on the formation and proliferation of glioblastoma-stem like cells is no less than Rac1." (PMID 28160553, 2017).
lung adenocarcinoma (7 papers, 2019 to 2024). A carcinoma that arises from the lung and is characterized by the presence of malignant glandular epithelial cells. "To investigate the molecular mechanisms underlying RAC3-associated paclitaxel resistance, we employed a strategy to generate paclitaxel-resistant lung adenocarcinoma cells." (PMID 38200409, 2024). "Rac3 expression was shown to be higher in lung adenocarcinoma tissues than in normal tissues and was an independent risk factor for N stage, which was associated with poor survival." (PMID 34257551, 2021). "The results explained that the high expression of UBE2C, UCHL1, TRAIP, TNNT1, TNNI3, and RAC3 were associated with poor overall survival of lung adenocarcinoma patients (p < 0.05)." (PMID 33050659, 2020). "In our previous study, we found that RAC3 was overexpressed in A549 paclitaxel-resistant lung adenocarcinoma cells." (PMID 38200409, 2024). "At the same time, we found that PSD can significantly inhibit the expression of RAC3 in paclitaxel-resistant lung adenocarcinoma cells, and the inhibitory effect is time- and concentration-dependent." (PMID 38200409, 2024). "Our results show that Ras-related C3 botulinum toxin substrate 3 (RAC3) is overexpressed in cultured paclitaxel-resistant cells and that RAC3 expression levels are negatively correlated with sensitivity of lung adenocarcinoma cells to paclitaxel." (PMID 38200409, 2024). "To validate the notion that RAC3 promotes paclitaxel-resistant lung adenocarcinoma cell proliferation and survival through the activation of PI3K/AKT signaling, we treated A549 cells overexpressing RAC3 with 10 μM Ly294002, an inhibitor of PI3K." (PMID 38200409, 2024). "Rac3 is a potential marker of invasion/metastasis and a therapeutic target also for lung adenocarcinoma." (PMID 31514269, 2019). "We proceeded to investigate the expression of the RAC3 gene in paclitaxel-resistant lung adenocarcinoma cells and examined whether its levels were affected by treatment with paclitaxel or PSD." (PMID 38200409, 2024). "We propose that PSD may increase the sensitivity of lung adenocarcinoma cells to PTX by inhibiting RAC3/PI3K/AKT." (PMID 38200409, 2024). "To test whether RAC3 is involved in the development of paclitaxel resistance in lung adenocarcinoma cells, we increased the expression of RAC3 in sensitive cells and decreased the expression of RAC3 in resistant cells." (PMID 38200409, 2024). "In summary, our findings from in vitro and in vivo studies support the hypothesis that PSD, when used in combination with paclitaxel, can effectively downregulate RAC3 expression and inhibit paclitaxel resistance in lung adenocarcinoma cells." (PMID 38200409, 2024). "PSD inhibits RAC3 expression in paclitaxel-resistant lung adenocarcinoma cells." (PMID 38200409, 2024). "PSD may inhibit the proliferation of paclitaxel-resistant lung adenocarcinoma cells by reducing RAC3 expression." (PMID 38200409, 2024). "Based on this observation, we formulated a hypothesis that PSD, in combination with paclitaxel, could be utilized to downregulate RAC3 and inhibit paclitaxel resistance in lung adenocarcinoma cells." (PMID 38200409, 2024). "This suggests that PSD may inhibit the proliferation of paclitaxel-resistant lung adenocarcinoma cells by reducing RAC3 expression." (PMID 38200409, 2024). "Indeed, Rac3 expression is significantly higher in lung adenocarcinoma compared with paired normal tissues, and the analysis of Rac3 expression in lung adenocarcinoma shows that positivity for Rac3 is associated with worse survival outcomes compared to Rac3 negative tumors." (PMID 31514269, 2019). "At the same time, we observed that low expression of RAC3 inhibited the phosphorylation levels of PI3K and AKT in paclitaxel-resistant lung adenocarcinoma cells." (PMID 38200409, 2024).
lung adenocarcinoma (continued). "Given the inhibitory effect of PSD on the proliferation of paclitaxel-resistant lung adenocarcinoma cells, we hypothesized that PSD might also impact RAC3 expression in this cellular context." (PMID 38200409, 2024). "In this study, Rac3 silencing inhibits lung adenocarcinoma cell migration and invasion in vitro and decreases the activity of the p38 MAPK pathway that is required for Rac3-induced migration and invasion, and for Rac3 regulated epithelial to mesenchymal transition." (PMID 31514269, 2019).
prostate carcinoma (7 papers, 2007 to 2024). A carcinoma that arises from epithelial cells of the prostate gland. "As early as 2007, prostate carcinomas have shown higher RAC3 expression levels than their normal controls." (PMID 37386813, 2023). "All prostate carcinomas analyzed exhibit markedly higher Rac3 protein expression levels than the respective normal counterparts." (PMID 31514269, 2019). "Expression of RAC-3 (also known as SRC-3) was higher in prostate cancer cell lines expressing the AR and has been shown to promote ligand-independent activation of the Akt pathway." (PMID 19675761, 2007). "RAC-3 mRNA and protein expression in prostate cancer cells has been shown to correlate with tumor grade and stage and increased expression correlates with poor survival in clinical studies." (PMID 19675761, 2007). "RAC3 is an important co-activator of androgen receptor, in the prostate, and it may have a significant role in prostate cancer progression." (PMID 38200409, 2024). "Interestingly, on average there is a three-fold increase in the ratio of Rac3/Rac1 expression levels in all prostate carcinomas when compared with the respective normal counterparts." (PMID 31514269, 2019). "Rac3 negatively regulates diapedesis of prostate cancer cell PC3, since knockdown of Rac3 using Rac3 specific siRNA increased migration of PC3 cells through a bone marrow endothelial cell layer." (PMID 24684802, 2014).